HSF2 (heat shock transcription factor 2)
Description:
DNA-binding protein that specifically binds heat shock promoter elements (HSE) and activates transcription. In higher eukaryotes, HSF is unable to bind to the HSE unless the cells are heat shocked.
Synonyms: HSF 2; HSTF 2
Tractability: PROTAC: UniProt records ubiquitination sites on it; ubiquitination databases record sites on it.
Gene: Protein-coding gene on chromosome 6 (122,399,551 to 122,433,119, forward strand). Ensembl gene ENSG00000025156.
Subcellular location: Cytoplasm; Nucleus
Subcellular location (Human Protein Atlas): Nucleoplasm
Gene Ontology:
Molecular function: DNA-binding transcription activator activity, RNA polymerase II-specific; protein binding; RNA polymerase II cis-regulatory region sequence-specific DNA binding; RNA polymerase II intronic transcription regulatory region sequence-specific DNA binding; RNA polymerase II transcription regulatory region sequence-specific DNA binding; sequence-specific double-stranded DNA binding; DNA-binding transcription factor activity, RNA polymerase II-specific; DNA binding; DNA-binding transcription factor activity; identical protein binding; sequence-specific DNA binding
Biological process: positive regulation of transcription by RNA polymerase II; regulation of transcription by RNA polymerase II; regulation of DNA-templated transcription
Cellular component: nucleoplasm; chromatin; cytoplasm; nucleus
Genetic constraint (gnomAD): Loss-of-function variants: 5 observed, 25.68 expected, observed/expected ratio (o/e) 0.19, 90% interval 0.1 to 0.41. The upper end of that interval is the gene's LOEUF score, 0.41, which puts it in group 1 of 6, group 1 being the genes least tolerant of losing a copy. Missense variants: 263 observed, 341.37 expected, observed/expected ratio (o/e) 0.77, 90% interval 0.7 to 0.85. Synonymous variants: 118 observed, 126.65 expected, observed/expected ratio (o/e) 0.93, 90% interval 0.8 to 1.09.
Homologues: Orthologues: chimpanzee HSF2 (100% identical), macaque HSF2 (99% identical), dog HSF2 (98% identical), pig HSF2 (97% identical), guinea pig HSF2 (94% identical), rat Hsf2 (94% identical), rabbit HSF2 (94% identical), mouse Hsf2 (92% identical), tropical clawed frog hsf2 (65% identical), zebrafish hsf2 (52% identical), Caenorhabditis elegans hsf-1 (25% identical), Drosophila melanogaster Hsf (24% identical). Paralogues in human: HSF1 (37% identical), HSF4 (30% identical), HSFY1 (13% identical), HSFY2 (13% identical), HSF5 (12% identical), HSFX1 (10% identical), HSFX2 (10% identical), HSFX4 (9% identical), HSFX3 (9% identical).
Diseases named in the same sentence as HSF2 in open-access papers:
HSF2 is named in the same sentence as 79 diseases in open-access papers, as found by Europe PMC text mining. Sharing a sentence is not in itself a finding about the gene and the disease. The quoted sentences say what the papers report.
breast carcinoma (15 papers, 2014 to 2025). "In many solid tumors, HSF1 and HSF2 interact and together modulate subsets of genes fundamental for disease progression, whereas in breast cancer HSF2 alone has been shown to promote the abnormal proliferation of cancer cells." (PMID 40245053, 2025). "During acute stress the interplay between HSFs sustains an optimal cellular response, whereas in other physiological and pathological processes such as erythroid differentiation and breast cancer progression, HSF2 operates independently from HSF1." (PMID 40245053, 2025). "In breast cancer cells, HSF2 regulates ALG3 enzyme expression to enhance cell proliferation and migration." (PMID 34917120, 2021). "In breast cancer cells, HSF2 has been identified to mediate transcription of the miR-183/-96/-182 cluster, which is highly expressed to promote tumorigenesis by directly regulating RAB21 expression." (PMID 35087869, 2021). "Several previous studies have indicated that HSF2 expression is altered in several types of cancer, including breast cancer, ESCC, lung cancer and prostate cancer." (PMID 34917120, 2021). "In breast cancer cells, HSF2 and the transcription factor zinc finger E-box-binding homeobox 1 (ZEB1) enhance tumorigenesis by cooperatively stimulating the expression of the microRNA cluster miR-183/-96/-182." (PMID 32408596, 2020). "Nevertheless, both HSF4 and HSF2 have been indicated to modulate the expression of hypoxia-inducible factor 1-alpha (HIF-1α) in MCF-7 breast cancer cells." (PMID 32408596, 2020). "MiR-96 and miR-183 weree lower in ER+ and PR+ breast cancers than ER- and PR- breast cancers; in the meantime, their regulator, HSF2 level was lower and their target, RAB21 level, was higher in ER+ and PR+ breast cancers than ER- and PR- breast cancers." (PMID 25394902, 2014). "HSF2 level was high in basal breast cancers, which are miR-183-enriched breast cancers; and RAB21 level was low in HER2 and basal breast cancers, which are miR-96- and/or miR-183-enriched breast cancers." (PMID 25394902, 2014). "This context‐dependent role of HSF2 in cancer is supported by several studies, as HSF2 has been reported to promote proliferation in different cancers, including hepatocellular carcinoma and breast cancer, but can also act as a suppressor of prostate cancer invasion." (PMID 40457168, 2025). "High levels of HSF2 facilitate the proliferation and invasion of breast cancer cells." (PMID 34917120, 2021). "HSF2 is also dysregulated in breast cancer cells to modulate their proliferation and invasion." (PMID 35087869, 2021). "Interestingly, HSF1 and HSF2 displayed the second highest correlation, providing evidence in support of a cooperative interaction in breast cancer." (PMID 33184288, 2020). "Since previous results had already indicated that HSF4 can modulate the expression of HIF-1α in MCF-7 breast cancer cells, it is possible that, similarly to HSF2, the function of HSF4 is hijacked in HCC in order to enhance HIF-1α expression, thereby allowing cancer progression." (PMID 32408596, 2020). "The functional impact of HSF2 on breast cancer has only recently started to emerge." (PMID 32408596, 2020). "Transcription of the cluster is regulated by ZEB1 and HSF2 in breast cancer cell lines." (PMID 29141042, 2017). "In HCC, breast cancer, prostate cancer, lung cancer, esophageal squamous cell carcinoma (ESCC), and colorectal cancer (CRC), HSF2 and HSF4 are frequently dysregulated, while HSF1 is highly expressed across all these cancers." (PMID 39248163, 2024). "In breast cancer, the transcription of miR-183 was regulated by ZEB1 and HSF2, HSF2 can upregulate miR-183 expression." (PMID 32047538, 2020). "To validate our procedure, we used the HSF2 gene, a close neighbor of GJA1 on chr6q22 which shares similar copy number in 99% of TCGA’s breast cancer cases." (PMID 29495625, 2018). "We identified two regulators (ZEB1 and HSF2) and one target gene (RAB21) for the miR-183/-96/-182 cluster in breast cancer cell lines." (PMID 25394902, 2014).
breast carcinoma (continued). "In addition to HSF2- miR-183/-96/-182 cluster pathway, HSF2-ALG3 pathway was discovered in breast cancer growth mechanism." (PMID 36430241, 2022). "Moreover, HSF2 mediates expression of the ALG3 enzyme, which subsequently promotes the growth and migration of breast cancer cells." (PMID 35087869, 2021). "Many genetic association studies have documented the potential impact of HSF1 and HSF2 on human health and diseases and tried to connect HSF1 gene variantsand its altered levels, to schizophrenia, bipolar disorder, attention deficit hyperactivity disorder and breast cancer." (PMID 35540693, 2021).
prostate carcinoma (11 papers, 2017 to 2025). A carcinoma that arises from epithelial cells of the prostate gland. "The expression of HSF2 is low in most of the prostate cancer tissues, which is mainly due to a heterozygous loss of HSF2, and low HSF2 expression correlates with increased metastasis and poor patient survival as well as a high Gleason score." (PMID 32408596, 2020). "Under these circumstances, Nees and Sistonen’s group reported that HSF2 suppresses tumor invasion of prostate cancer." (PMID 36430241, 2022). "In the same way, low level of HSF2 mRNA was also observedin different types of malignancies in humans like invasive breast carcinoma, prostate carcinoma and various other carcinomas." (PMID 35540693, 2021). "In contrast to HSF1, HSF2 appears to function as a tumor suppressor in prostate cancer." (PMID 32408596, 2020). "While the molecular mechanism by which HSF2 suppresses prostate cancer development remains to be established, a gene expression profiling indicated that HSF2 modulates GTPase activity, cell–cell adhesion, and actin cytoskeleton dynamics, all of which have altered expression in cancer." (PMID 32408596, 2020). "During the progression of prostate cancer, a decrease in HSF2 expression has been observed, which could at least partly be due to cancer cells’ property to eliminate an HSF2-driven transcriptional program." (PMID 32408596, 2020). "Importantly, a meta-analysis demonstrated that in addition to prostate cancer, the mRNA expression of HSF2 is downregulated in a variety of cancer tissues, suggesting that HSF2 downregulation is a key event during cancer development." (PMID 32408596, 2020). "To date, only Fan and his colleagues reported that HSF2 is positively involved in esophageal squamous cell carcinogenesis; however, aberrant regulation of miR-202 was also reported in human osteosarcoma, colorectal carcinoma, lung cancer, pancreatic cancer, bladder cancer, and prostate cancer." (PMID 36430241, 2022). "HSF2 has also been reported to be involved in cancer development but appears to act as a tumor suppressor as it HSP2 expression is frequently decreased in multiple tumor types and silencing of HSF2 leads to invasion in prostate cancer cell lines." (PMID 28914774, 2017).
Infertility (8 papers, 2019 to 2025). "It is still important to discover the mutations in the HSF2 gene involved in infertility, but it must also be important to reveal the mechanism of how Arg502His mutant HSF2 loses its functions completely." (PMID 36430241, 2022). "The first azoospermic patients (patients with infertility) with HSF2 loss-of-function mutation have been discovered by Gui and his colleagues in 2013." (PMID 36430241, 2022). "In a word, our study revealed a novel missing insertion mutation c.326_326delinsGGAAGGTGAGCTATTGT in HSF2 which expanded the mutation spectrum of HSF2 in Chinese NOA infertile men and advanced our understanding of the genetic susceptibility to NOA." (PMID 32756090, 2020). "The low expression and hypermethylation of HSF2 could be potential causes of the obstruction of spermatogenesis, which leads to male cattle-yak infertility." (PMID 38791628, 2024). "Therefore, we suggest more studies to investigate the role HSF2 in dams’ infertility caused by AMDV." (PMID 38200094, 2024). "In 2020, Liu and his colleagues reported that novel HSF2 mutation causes infertility." (PMID 36430241, 2022). "Cooperation between hsf1 and hsf2 is vital for fertility in both sexes, with inactivation of these genes resulting in failures in gametogenesis and infertility." (PMID 40427320, 2025). "Taken together, the low expression abundance and hypermethylation of HSF2 may underpin the obstruction of spermatogenesis, which leads to male cattle-yak infertility." (PMID 38791628, 2024). "However, none of theSNPs in HSF1 and HSF2 genes is linked with infertility in men in the study cohort." (PMID 35540693, 2021). "However, data on genetic variations in HSF1, HSF2 and UBE2I genes for infertility in males is scanty." (PMID 35540693, 2021).
lung carcinoma (7 papers, 2020 to 2025). "We generated HSF1 mutants with lysine-to-arginine substitutions at five SUMOylation sites and studied their function in H1299 lung carcinoma cells with HSF1/HSF2 knockout, which lack a functional HSR." (PMID 40617887, 2025). "To treat lung cancer patients, we must investigate and find drugs and therapeutics controlling HSF2 activity." (PMID 36430241, 2022). "Wang and his colleagues examined lung cancer tissues, and discovered that the expression level of HSF2 mRNA is significantly upregulated in lung cancer tissues compared to normal tissues." (PMID 36430241, 2022). "HSF2 has been reported to be expressed at high levels in patients with lung cancer and affects the growth and migration of lung cancer cells by regulating the expression of HSPs." (PMID 35087869, 2021). "HSF2 is aberrantly expressed in lung cancer and influences cancer cell growth and migration by acting as an upstream regulator of HSPs." (PMID 34917120, 2021). "Similarly to HSF1, the expression of HSF2 has been found to be upregulated in tumor tissues from lung cancer patients." (PMID 32408596, 2020). "However, unexpectedly, only two papers reported that HSF2 has a relationship with lung cancer." (PMID 36430241, 2022). "There may be a non HSF2-mediated cancerous pathway or mechanism as HSF2 protein is expressed enough in lungs; therefore, there must be a HSF2-mediated essential mechanism in lung cancer generation or progression." (PMID 36430241, 2022). "Hence, it is possible that USF2 stimulates HSF2 expression also in lung cancer." (PMID 32408596, 2020). "As already described in Section 2 of this paper, they also showed that overexpression of HSF2 by transfection increased the expression of HSP27, HSP47, HSP70, and HSP90 proteins in both normal lung epithelial and lung cancer cells." (PMID 36430241, 2022). "As already described, overexpression of HSF2 can increase the expression of not only HSP70 but also HSP27, HSP47, and HSP90 in normal lung epithelial and lung cancer cells." (PMID 36430241, 2022). "Although it is not yet known by which mechanisms HSF2 expression is enhanced in lung cancer cells, there is a disease-specific correlation between the high expression of HSF2 and the transcription factor USF2 in A549 lung cancer cells." (PMID 32408596, 2020). "In non-tumorigenic BEAS-2B cells and A549 lung cancer cells, the elevated levels of HSF2 promote cell proliferation and migration, which is partially dependent on HSF2’s ability to induce the expression of HSP27/HSPB1 and HSP90/HSPC." (PMID 32408596, 2020). "Wang and his colleagues reported that the overexpression of HSF2 conjugated with Enhanced Green Fluorescent Protein (EGFP) by transfection increases HSP27, HSP47, HSP70, and HSP90 proteins in both human normal lung epithelia BEAS-2B and human lung cancer A549 cells." (PMID 36430241, 2022).
ulcerative colitis (6 papers, 2014 to 2025). An inflammatory bowel disease involving the mucosal surface of the large intestine and rectum. "A recently study showed that HSF2 was upregulated in ulcerative colitis and was negatively associated with colon inflammation in mice." (PMID 35087869, 2021). "A previous study showed that HSF2 is upregulated in ulcerative colitis and increases the production of inflammatory cytokines." (PMID 34917120, 2021). "The expression of heat shock factor 2(HSF2)in colonic mucosa in Crohn's disease, Behcet's disease, ulcerative colitis, intestinal tuberculosis, infective enteritis, intestinal lymphoma, and normal controls was investigated by immunohistochemistry (IHC)." (PMID 24533153, 2014). "Interestingly, a similar stress-induced increase in HSF2 expression has also been reported in human ulcerative colitis patients." (PMID 27626448, 2016).
cardiac hypertrophy (5 papers, 2017 to 2025). "•The data provide information about the deSUMOylation HSF2 by MEL18 for cardiac hypertrophy is significant in adult hypertensive human heart, compared to adult healthy human heart." (PMID 29270451, 2018). "Taken together, these results indicated that HSF2 activation contributed to cardiac hypertrophy via IGF-IIR signaling." (PMID 28796250, 2017). "In this study, we found that HSF2 activated IGF-IIR to induce cardiac hypertrophy during hypertension-induced heart failure." (PMID 28796250, 2017). "HSF2 selectively activates the biogenesis of IGF-IIR for cardiac hypertrophy during hypertension-induced heart failure." (PMID 28796250, 2017). "Inhibition of HSF2 SUMOylation induced cardiac hypertrophy in hypertensive rats." (PMID 34638970, 2021). "Former study has demonstrated that HSF2 could induce cardiac hypertrophy during hypertension-induced heart failure by the activation of IGF-IIR." (PMID 34530741, 2021). "•The data presents ANG II mediated MEL18 to deSUMOylate HSF2, leading to cardiac hypertrophy." (PMID 29270451, 2018). "We identified HSF2 as a miR-18 target for cardiac hypertrophy." (PMID 28796250, 2017). "However, the role of heat shock factor 2 (HSF2) in hypertension-induced cardiac hypertrophy is unknown." (PMID 28796250, 2017). "Loss ofmiRNA-18 in the heart severely impairs cardiac functions by triggering heat shocktranscription factor 2 (HSF2) and IGF-IIR (insulin growth factor receptor II),which leads to induce cardiac hypertrophy during hypertension." (PMID 40475735, 2025). "We showed that miR-18 was required for HSF2 suppression and indispensable for the regulation IGF-IIR signaling during cardiac hypertrophy and cardiac functions by maintenance of cardiomyocyte shapes for heart function." (PMID 28796250, 2017). "Taken together, these results demonstrated that ANG II destroyed miR-18 targeting to the miR-18-HSF2-3′UTR to upregulate HSF2 expression, leading to the activation of IGF-IIR-mediated cardiac hypertrophy." (PMID 28796250, 2017). "Our results showed that HSF2 positively regulated IGF-IIR transcription, which led to cardiac hypertrophy under hypertension-induced heart failure conditions, whereas HSF1 markedly inhibited IGF-IIR transcription to protect cardiomyocytes from hypertension-induced heart failure." (PMID 28796250, 2017). "Finally, HSF2 upregulated IGF-IIR, thereby contributing to cardiac hypertrophy." (PMID 28796250, 2017).
esophageal squamous cell carcinoma (5 papers, 2019 to 2024). Esophageal squamous cell carcinoma (ESCC) is a type of esophageal carcinoma (EC) that can affect any part of the esophagus, but is usually located in the upper or middle third. "Also, the DmiR miR202 induces esophageal squamous cell carcinoma (ESCC) dormancy by regulating heat shock transcription factor 2 (HSF2) and its target gene, HSP70, hence suppressing ESCC in a dormancy state, and vice versa." (PMID 38994941, 2024). "In esophageal squamous cell carcinoma (ESCC), miR-202 acts as a tumor suppressor by regulating HSF2 and its target gene HSP70." (PMID 31557887, 2019).
heart failure (5 papers, 2017 to 2021). Inability of the heart to pump blood at an adequate rate to meet tissue metabolic requirements. "DOX-induced mitochondrial reactive oxygen species (ROS) release was demonstrated to activate ERK-mediated heat shock factor 2 (HSF2) nuclear translocation and AT1 R upregulation, which caused DOX-damaged heart failure." (PMID 33281914, 2020).